CXCL13 (C-X-C motif chemokine ligand 13)
Diseases named in the same sentence as CXCL13 in open-access papers (continued):
Sharing a sentence is not in itself a finding about the gene and the disease.
ovarian carcinoma (continued). "Furthermore, elevated expression of the CXCL13 gene has been linked to improved prognosis in various cancers, including CRC and ovarian cancer." (PMID 39177263, 2024). "The result only shows a good agreement between CXCL13 and tumor stemness score in ovarian cancer." (PMID 38459390, 2024). "We also investigated whether CXCL13 was associated with TLS formation and improved the prognosis of patients with ovarian cancer." (PMID 35552285, 2022). "The consequence of CXCL13 in ovarian cancer is gradually understood." (PMID 36704336, 2022). "The up-regulated gene expression of CXCL13 has been proven to be associated with better prognosis in oral cancer, bladder cancer, and ovarian cancer, and CXCL13 was significantly lower in patients with metastatic thyroid cancers, which was associated with an abundance of inefficient Tfh cells." (PMID 36497450, 2022). "Because there was a correlation between CXCL13 and PD-1/PD-L1 gene expression, we hypothesized that CXCL13 had an adjuvant effect in HM-1 ovarian cancer models that were originally refractory to anti–PD-1/PD-L1 antibody therapy." (PMID 35552285, 2022). "The effect of CXCL13 on TLS formation in tumors was analyzed using a mouse ovarian cancer model." (PMID 35552285, 2022). "Moreover, the expression of TAP1 and CXCL13 were indeed increased in ovarian cancer tissues through experimental verification." (PMID 34631788, 2021). "We found that, in ovarian cancer, the expression of CXCL13, INFG, CD30, and PRF1 genes predicted favorable prognosis, and that CXCL3, INFG, and PRF1 were associated with an increased infiltration level of CD8+ T cells and dendritic cells and neutrophils within the tumor." (PMID 31998644, 2019). "As the cancer cells tested do not express CXCL13 (a ligand for CXCR5), the novel role of CXCR5 in ovarian cancer cells in response to EGF or TNF may highlight their interaction with immune cells expressing CXCL13 in the tumor microenvironment." (PMID 23800251, 2013). "Several studies have demonstrated that high levels of CXCL13+ cells or CXCL13 expression in the TME could be used as a prognostic biomarker for ICI-treated bladder cancer and ovarian cancer patients and is associated with prolonged survival and objective response." (PMID 38398098, 2024). "CXCL13 could enhance the effectiveness of PD-1 blocking therapy in ovarian cancer." (PMID 34736480, 2021). "Alternatively, inducing CD4+ expression of CXCL13 allowed the formation of TLS and improved the leucocyte infiltration in ovarian cancer." (PMID 38333212, 2024). "In ovarian cancer, CD21+ FDCs are the main CXCL13 source for late-stage TA-TLS maturation and play a crucial role in the organization and maintenance of GCs." (PMID 39569184, 2024). "A subcluster of terminal Tex cells from ovarian cancer express FOXP3, a dominant transcription factor in Treg cells, and these CD8+FOXP3+ T cells shared TCRs with CXCL13+ cells." (PMID 38519500, 2024). "For instance, in ovarian cancer, CD8+ cytotoxic T lymphocytes (CTLs) producing CXCL13 have been shown to promote the development of TLS and contribute to antitumor responses." (PMID 39344390, 2024). "In ovarian cancer, both CD8+ T cells and CD4+ T cells were observed to be the origin of CXCL13 and play important roles in mediating B-cell recruitment and TLS formation in human tumors." (PMID 39569184, 2024). "Studies have shown that CDK4/6 inhibition combined with PD-1 blockade treatment has higher CXCL10 and CXCL13 levels and CD8 + and CD4 + T cell activity than monotherapy-treated ovarian cancer." (PMID 37005667, 2023). "In contrast, it was reported that infiltration of CXCL13-producing CD4+ T cells precedes HEV and TLS formation in the ovarian cancer microenvironment." (PMID 37476074, 2023). "Combining an oral FAK inhibitor with TIGIT-blocking antibody immunotherapy increased TILs and CXCL13 levels, leading to TLS formation and prolonged survival in experimental mouse models of aggressive ovarian cancer." (PMID 38023214, 2023).
ovarian carcinoma (continued). "They applied single-cell RNA sequencing analysis to patient-derived samples of head and neck, cervical, and ovarian cancer to detect the expression of transcription factor TOX and the chemokine CXCL13." (PMID 35053457, 2022). "CIBERSORT using the microarray data of ovarian cancer cases registered in The Cancer Genome Atlas (TCGA) confirmed a wide range of CXCL13 expression in TME and that CXCL13 expression correlated with the infiltration of various TILs." (PMID 35552285, 2022). "CXCL13 gene expression in tumors is significantly correlated with the presence of TLS, lymphocyte infiltration, and a favorable prognosis for ovarian cancer." (PMID 35552285, 2022). "Accordingly, our results clearly demonstrate that the induction of CXCL13 and TLS has potential as an immune-modulatory target for ovarian cancer." (PMID 35552285, 2022). "To investigate which factors promote CXCL13 secretion from CD4+ T cells and CD8+ T cells, we analyzed 2 sets of gene expression data from ovarian cancer tissues." (PMID 35552285, 2022). "Currently, although numerous molecular subtyping has been developed in ovarian cancer, such as IFNG, CD30, CXCL13, PRF1 GBP1, and ETV7 CTLA-4, they provided limited prognostic information or are not validated in the clinical samples." (PMID 36157232, 2022). "As for ovarian cancer, previous studies proposed that TLS coordinates the infiltration of T cells, such as the cytotoxic T cell and CXCL13-producing CD4+ T cells, and antibody-producing PCs to advance antitumor responses." (PMID 36704336, 2022). "Researchers were trying to find reliable immune-related prognostic genes in ovarian cancer, including TAP1 and CXCL13." (PMID 34631788, 2021). "The transcriptional levels of CXCL1, CXCL8, CXCL10, CXCL11, CXCL12, CXCL13, and CXCL14 were significantly elevated while CXCL3 was obviously reduced in ovarian cancer vs normal ovarian tissue." (PMID 33763130, 2021). "We found that the combined expression of IFNG, CD30, CXCL13, and PRF1 correlated with better overall survival (OS) in advanced stage ovarian cancer." (PMID 31998644, 2019). "Also, ascites in obese mice have higher levels of macrophages and chemokines including CXCL13, suggesting that obesity may accelerate the peritoneal dissemination of ovarian cancer through higher production of pro-inflammatory chemokines and macrophages recruitment." (PMID 31354634, 2019). "In an ovarian cancer mouse model, CXCL13 in conjunction with anti-PD-1 therapy resulted in tumor infiltration with CXCR5+CD8+ T cells and improved survival, further underscoring the role of CXCL13 as key chemoattractant in ICI-treated cancers." (PMID 38928238, 2024). "In ovarian cancer, M1-type macrophages, but not M2-type macrophages, are one of the sources of CXCL13, which is important for TLS formation." (PMID 39569184, 2024). "PCR and cytokine array methods were applied to detect cytokine and chemokine levels, which revealed that ID8 ovarian cancer cells secrete higher levels of CXCL10 and CXCL13 after CDK4/6i treatment resulting in increased lymphocytes infiltration in the tumor microenvironment." (PMID 35053457, 2022). "A mouse ovarian cancer cell line OV2944-HM-1 (HM-1) was i.p. inoculated to B6C3F1 immunocompetent mice, and mouse recombinant CXCL13 (rCXCL13) was i.p. administered 5 times every other day starting from day 1, and TLS formed in the omental tumor were evaluated on days 10–12." (PMID 35552285, 2022). "First, we did not directly prove that CXCL13 secreted from CD4+ T cells induced TLS in the mouse ovarian cancer model." (PMID 35552285, 2022). "We also observed that the CXCL13-producing CD4 + T cells could facilitate the formation of TLS and strengthen the cooperative antitumor activity of cellular and humoral immunity in ovarian cancer." (PMID 36704336, 2022). "Finally, a nomogram model for advanced ovarian cancer based on TAP1 and CXCL13 was established for the first time." (PMID 34631788, 2021).
ovarian carcinoma (continued). "In addition, as seen in ovarian cancer, there was also a clear link between the expression of IFNG, CXCL13, CD30, and PRF1 and presence of immune cells within the tumor, including B cells, CD8+ T cells, CD4+ T cells, dendritic cells, and neutrophils." (PMID 31998644, 2019). "Many of the same proteins that were identified by unsupervised hierarchical clustering and by linear regression analysis, were also significantly higher in the late stage ovarian cancer patients relative to the healthy women, e.g. MK, KLK6, hk11, CXCL13, FR-alpha, IL-6, and FADD." (PMID 29051715, 2017). "The remaining three proteins (CXCL13, PARK7, and LAP.TGF-β1) do not appear in the literature as having an association with ovarian cancer, however they have been identified in other types of cancer." (PMID 29051715, 2017). "Linear regression analysis of our Proseek® data had found six of these proteins to have a statistically significantly trend (p < 0.001); CA125, CXCL13, CD40L, CD69, and LAP.TGF-β1 levels were higher in ovarian cancer serum samples, while EGFR levels were lower." (PMID 29051715, 2017). "Three of these proteins, CXCL13, FADD, and TNFSF14 have not been reported in the literature as having an association with ovarian cancer, and may serve as novel candidate biomarkers for ovarian cancer." (PMID 29051715, 2017). "Thus, the scoring model based on the gene expressions of CXCL13, IDO1, PI3, SPP1 and TRIM22 from GSE15622 dataset and constructed by lasso algorithm could better predict the sensitivity of ovarian cancer patients to chemotherapeutic drugs than which based on single gene." (PMID 34736480, 2021). "Notably, CXCL13, TNFSF14, and FADD had not been previously identified in ovarian cancer tissues or serum." (PMID 29051715, 2017).
lung carcinoma (49 papers, 2015 to 2025). "CXCL13 is important for monitoring SjS and plays a role in lung cancer diagnosis, with studies showing upregulated CXCL13 in 90% of non-small-cell lung cancer cases, linked to neovascularization and tumorigenesis." (PMID 39682582, 2024). "It is interesting to note that, in lung cancer patients, CXCL13-high tumors were associated with more TLSs and correlated with longer OS as well as an improved response to PD-1 blockade." (PMID 36077836, 2022). "Conclusively, these results identify the crucial role of CXCR5 receptor in regulating cell migration and VCAM‐1 expression, which caused by CXCL13 incubation in lung cancer cells." (PMID 34427969, 2021). "Deficiency in Cxcl13 or its receptor, Cxcr5, significantly attenuated BaP-induced lung cancer in mice, demonstrating CXCL13’s critical role in PAH-induced lung carcinogenesis." (PMID 26565418, 2015). "Additionally, the relevance of CXCL13 expression in macrophages was implicated in lung cancer promoted by Benzo (a) pyrene (BaP), a carcinogen found in tobacco smoking." (PMID 36217194, 2022). "Also, CXCL13/CXCR5 axis contributed to cell motility in lung cancer cells, which was caused by VCAM‐1 expression." (PMID 34427969, 2021). "Interestingly, deficiency in CXCL13 or CXCR5 significantly inhibits BaP-induced lung cancer in mice, indicating the critical role of this axis in environmental lung carcinogenesis." (PMID 34947813, 2021). "For instance, the presence of functional tertiary lymphoid structures has been associated with long-term survival in lung cancer patients, and signaling by CXCL13, among other chemoattractants, has been shown to mediate T-cell recruitment to tertiary lymphoid structures." (PMID 31354634, 2019). "This shows that CXCL13 signalling is an important mechanism by which PAHs cause lung cancer." (PMID 26565418, 2015). "The relative expression of CXCL13 in malignant pleural effusions caused by lung tumors may indicate a poor prognosis, and it is expected to become a new indicator for screening and prognosis of patients with advanced lung cancer." (PMID 37025603, 2023). "Because DEX is a wide-spectrum anti-inflammatory drug that may cause severe side effects, more specific, CXCL13/CXCR5-targeting antibodies or small molecules should be developed to combat lung cancer, the leading cause of cancer-related mortality accounting for 1.59 million deaths worldwide in 2012." (PMID 26565418, 2015). "A few reports regarding breast and lung cancers have shown that the CXCL13/CXCR5 axis attracts B cells to form TLSs at peritumoral or tumor sites." (PMID 39611128, 2024). "In a subsequent animal model-based mechanistic study administering recombinant CXCL13 to mice with lung cancer, it was demonstrated that CXCL13 treatment enhanced therapeutic PD-1 blockade by increasing antigen-experienced T cell subsets." (PMID 39114657, 2024). "AhR mediates BaP-induced production of a chemokine CXCL13, the knockout of which significantly inhibits BaP-initiated lung cancer." (PMID 39042313, 2024). "Previous researches reported that NFκB pathway activation induced CXCL13-expression in lung cancer and osteosarcoma, promoting cell migration." (PMID 37045944, 2023). "Cochrane’s Q test did not provide evidence of heterogeneity between CCL14 (p = 0.916), CCL19 (p = 0.446), CCL20 (p = 0.130), CCL21 (p = 0.878), CCL27 (p = 0.762), CXCL9 (p = 0.340) and CXCL13 (p = 0.770) and lung cancer." (PMID 38075694, 2023). "This provides promising potential for using CXCL13 as a screening tool and prognostic indicator for patients with advanced lung cancer complicated by malignant pleural effusion." (PMID 37025603, 2023). "have revealed that SPP1+ macrophages and PDCD1+CXCL13+ activated T cells were correlated with the activation of lung cancer, indicating their essential role in cancer progression." (PMID 37846760, 2023).
lung carcinoma (continued). "In this study, Th7R was the only cluster in which we detected significant CXCL13 gene expression in all CD4+ T-cell clusters in the lung cancer microenvironment." (PMID 37476074, 2023). "Simultaneously, in the context of lung cancer, CXCL13 was considered to be a carcinogenic cytokine with significantly enhanced expression levels and facilitating cancer cell invasion through the epithelial-mesenchymal transition (EMT) process." (PMID 38075694, 2023). "In melanoma, lung cancer, and colorectal cancers, CXCL13, along with CCR5, has been identified as a T-cell-intrinsic marker of ICT sensitivity." (PMID 37488535, 2023). "BaP-induced lung tumors in mice displayed increased CXCL13 levels, while CXCL13 or CXCR5 knockout significantly suppressed the development of Bap-induced lung cancer." (PMID 36217194, 2022). "Our evidence showed that CXCL13 obviously promoted migration of lung cancer cells, and this effect was mediated by vascular cell adhesion molecule‐1 (VCAM‐1) expression." (PMID 34427969, 2021). "Here, we found that VCAM‐1, a cell adhesion molecule associated with metastasis, which was up‐regulated in response to CXCL13 in lung cancer cells." (PMID 34427969, 2021). "Our finding here supposes that CXCL13/CXCR5 axis is a major regulator of VCAM‐1 up‐regulation in lung cancer." (PMID 34427969, 2021). "Meanwhile, CXCR5 neutralized antibody also dose‐dependently reversed cell migration and VCAM‐1 expression in CXCL13‐treated lung cancer cells." (PMID 34427969, 2021). "Previous report showed that high levels of CXCR5 and CXCL13 were up‐regulated in tissues and sera of lung cancer patients respectively." (PMID 34427969, 2021). "Our present work provides novel application of CXCL13/CXCR5 axis in lung cancer therapeutic strategy." (PMID 34427969, 2021). "In conclusion, these evidences suggest that the CXCR5, PLCβ, PKCα and c‐Src signalling pathways mediate NF‐κB activation in lung cancer cells treated with CXCL13." (PMID 34427969, 2021). "In conclusion, our present study suggests that CXCL13/CXCR5 axis is up‐regulated in lung cancer cells, which promotes VCAM‐1 expression and further cell migration." (PMID 34427969, 2021). "Based on our finding here, the clinical relevance of CXCL13/CXCR5 in lung cancer progression and development of novel therapeutic targets should be addressed in the future." (PMID 34427969, 2021). "First, the mRNA expression level of CXCL13 in lung cancer was analyzed online by the Gene Expression Profiling Interactive Analysis (GEPIA) tool." (PMID 34553036, 2021). "Deficiency in CXCL13 or CXCR5 significantly suppressed BaP-induced lung cancer in mice, indicating that CXCL13 plays a key role in smohaze carcinogen-induced lung cancers." (PMID 34947813, 2021). "In this study, we found PLCβ/PKCα/c‐Src signal cascade was activated after CXCL13 treatment in lung cancer cells." (PMID 34427969, 2021). "This evidence suggests that CXCL13/CXCR5 axis activation is common feature in lung cancer progression." (PMID 34427969, 2021). "Anti-tumor activity of the CXCL13/CXCR5 axis has also been reported, which is shown to be able to promote the formation of TLSs and is linked to improved survival of lung cancer patients." (PMID 34947813, 2021). "The chemokine (C-X-C motif) ligand 13 (CXCL13) plays a vital role in the development of several cancers (e.g., gastric, colorectal, breast and lung cancers), the promotion of angiogenesis, and the metastatic cascade." (PMID 32847038, 2020). "A specific gene expression signature associated with T-cell presence in tertiary lymphoid structures was identified in human lung cancer, which includes CXCL13 and other chemokines." (PMID 31354634, 2019). "The relevance of CXCL13 in Ba[a]P-induced lung cancer was further confirmed using CXCL13 and CXCR5 knockout mice, which have impaired tumor formation in response to the carcinogen." (PMID 31354634, 2019).